ARIH2 (ariadne RBR E3 ubiquitin protein ligase 2)
Description:
E3 ubiquitin-protein ligase, which catalyzes ubiquitination of target proteins together with ubiquitin-conjugating enzyme E2 UBE2L3. Acts as an atypical E3 ubiquitin-protein ligase by working together with cullin-5-RING ubiquitin ligase complex (ECS complex, also named CRL5 complex) and initiating ubiquitination of ECS substrates: associates with ECS complex and specifically mediates addition of the first ubiquitin on ECS targets. The initial ubiquitin is then elongated. E3 ubiquitin-protein ligase activity is activated upon binding to neddylated form of the cullin-5 (CUL5) component of the ECS complex. Together with the ECS(ASB9) complex, catalyzes ubiquitination of CKB. Promotes ubiquitination of DCUN1D1. Mediates 'Lys-6', 'Lys-48'- and 'Lys-63'-linked polyubiquitination. May play a role in myelopoiesis. (Microbial infection) Following infection by HIV-1 virus, acts together with a cullin-5-RING E3 ubiquitin-protein ligase complex (ECS complex) hijacked by the HIV-1 Vif protein, to catalyze ubiquitination and degradation of APOBEC3F and APOBEC3G.
Synonyms: ARI2; TRIAD1
Tractability: PROTAC: UniProt records ubiquitination sites on it; ubiquitination databases record sites on it; its protein half-life has been measured.
Gene: Protein-coding gene on chromosome 3 (48,918,821 to 48,986,382, forward strand). Ensembl gene ENSG00000177479.
Subcellular location: Nucleus; Cytoplasm
Subcellular location (Human Protein Atlas): Nucleoplasm
Pathways (Reactome):
Immune System: Antigen processing: Ubiquitination & Proteasome degradation
Gene Ontology:
Molecular function: protein binding; ubiquitin conjugating enzyme binding; ubiquitin protein ligase activity; ubiquitin-protein transferase activity; zinc ion binding; metal ion binding
Biological process: developmental cell growth; hematopoietic stem cell proliferation; positive regulation of establishment of protein localization to mitochondrion; proteasome-mediated ubiquitin-dependent protein catabolic process; protein K48-linked ubiquitination; protein K63-linked ubiquitination; protein polyubiquitination; protein ubiquitination; ubiquitin-dependent protein catabolic process
Cellular component: Cul5-RING ubiquitin ligase complex; cytoplasm; nucleoplasm; nucleus; ubiquitin ligase complex
Genetic constraint (gnomAD): Loss-of-function variants: 9 observed, 64.99 expected, observed/expected ratio (o/e) 0.14, 90% interval 0.082 to 0.24. The upper end of that interval is the gene's LOEUF score, 0.24, which puts it in group 1 of 6, group 1 being the genes least tolerant of losing a copy. Missense variants: 273 observed, 596.54 expected, observed/expected ratio (o/e) 0.46, 90% interval 0.41 to 0.51. Synonymous variants: 209 observed, 210.36 expected, observed/expected ratio (o/e) 0.99, 90% interval 0.89 to 1.11.
Homologues: Orthologues: rabbit ARIH2 (99% identical), guinea pig ARIH2 (99% identical), pig ARIH2 (99% identical), chimpanzee ARIH2 (98% identical), mouse Arih2 (98% identical), dog ARIH2 (95% identical), macaque ARIH2 (95% identical), rat Arih2 (95% identical), tropical clawed frog arih2 (92% identical), zebrafish arih2 (81% identical), Drosophila melanogaster ari-2 (54% identical), Caenorhabditis elegans ari-2 (46% identical). Paralogues in human: ARIH1 (34% identical), ANKIB1 (31% identical), RNF19A (18% identical), RNF19B (17% identical), RNF14 (15% identical), RNF217 (14% identical), PRKN (13% identical), RNF144A (13% identical), RNF144B (12% identical).
Diseases named in the same sentence as ARIH2 in open-access papers:
ARIH2 is named in the same sentence as 30 diseases in open-access papers, as found by Europe PMC text mining. Sharing a sentence is not in itself a finding about the gene and the disease. The quoted sentences say what the papers report.
acute myeloid leukemia (5 papers, 2021 to 2025). Acute myeloid leukemia (AML) is a group of neoplasms arising from precursor cells committed to the myeloid cell-line differentiation. "Evidence indicates that ARIH2 significantly influences the development and progression of gastric cancer, acute myeloid leukemia, human non-small cell lung cancer, and other malignancies." (PMID 40260250, 2025). "Evidence indicates that ARIH2 plays an essential part in the development and progression of gastric cancer, acute myeloid leukemia, human non-small cell lung cancer, and other malignancies." (PMID 40260250, 2025). "Evidence has shown that ARIH2 plays an important role in the occurrence and development of acute myeloid leukemia, human non-small-cell lung cancer and other cancers." (PMID 35732617, 2022). "ARIH2 gene encodes an anti-proliferative E3 ubiquitin ligase, Triad1, which has a role in leukemogenesis, is induced by M11-E11 (MLL1 fusion protein) in acute myeloid leukemia." (PMID 34769401, 2021). "ARIH2 also inhibited the development of acute myeloid leukemia induced by the MLL1 fusion protein." (PMID 35732617, 2022). "Though the ARIH2 transcript amount in acute promyelocytic cell line (NB4) is low, suggesting a similar expression pattern in acute myeloid leukemia patients, an inclusive study aiming to evaluate its expression level in a cohort of patients affected by different myeloid disorders is lacking." (PMID 33477751, 2021).
leukemia (3 papers, 2018 to 2025). A malignant (clonal) hematologic disorder, involving hematopoietic stem cells and characterized by the presence of primitive or atypical myeloid or lymphoid cells in the bone marrow and the blood. "ARIH2 encodes TRIAD1, an E3 ubiquitin ligase required for termination of emergency granulopoiesis and leukemia suppressor function in MLL1-rearranged AML." (PMID 32467231, 2020).
autism spectrum disorder (2 papers, 2024). A spectrum of developmental disorders that includes autism, and Asperger syndrome. "Another example is Ube2l3, which is the E2 of the ligase enzyme ARIH2 very recently identified mutated in a patient with autism spectrum disorder and intellectual disability." (PMID 39596581, 2024).
gastric cancer (2 papers, 2022 to 2025). A primary or metastatic malignant neoplasm involving the stomach. "For instance, a recent study revealed that ARIH2 promotes the proliferation of gastric cancer cells by reducing p21 stability through ubiquitination." (PMID 40260250, 2025). "ARIH2 also decreases p21 stability via ubiquitination, influencing DNA damage and apoptosis in gastric cancer (GC) cells." (PMID 40260250, 2025). "In this paper, we found that high ARIH2 expression is correlated with poor prognosis in gastric cancer patients and that ARIH2 can significantly promote the proliferation of gastric cancer cells." (PMID 35732617, 2022). "The effect of ARIH2 knockdown on colony formation and tumorigenesis of gastric cancer cells was also shown both in vivo and in vitro." (PMID 35732617, 2022). "Generally, our results indicated that ARIH2 promotes the proliferation of gastric cancer cells and regulates p21 expression." (PMID 35732617, 2022). "In addition, ARIH2 knockdown induced DNA damage, and then induced cell apoptosis and regulated the chemosensitivity of gastric cancer cells after combined treatment with 5-fluorouracil." (PMID 35732617, 2022). "However, the molecular mechanism and biological function of ARIH2 in the pathogenesis of gastric cancer remain unclear." (PMID 35732617, 2022).
Intellectual disability (2 papers, 2024). "Although several studies have identified the strong role of ubiquitination in autism and intellectual disability, the association between ARIH2 gene and these conditions that we are proposing is only a hypothesis." (PMID 38982159, 2024).
autism (1 paper, 2024). Persistent deficits in social interaction and communication and interaction as well as a markedly restricted repertoire of activity and interest as well as repetitive patterns of behavior. "Within this context, two de novo variants were detected in 5’ UTR and intronic regions of ARIH2 gene, exhibiting an uncertain correlation with autism." (PMID 38982159, 2024).
hepatocellular carcinoma (1 paper, 2025). A malignant tumor that arises from hepatocytes. "Nevertheless, the underlying biological function of ARIH2 in the progression of hepatocellular carcinoma (HCC) remains ambiguous." (PMID 40260250, 2025).
intracerebral hemorrhage (1 paper, 2022). A cerebrovascular disorder characterized by bleeding into one or both cerebral hemispheres including the basal ganglia and the cerebral cortex. "Moreover, increased expression of ARIH2 was correlated with neuronal apoptosis after intracerebral hemorrhage in adult rats, indicating that ARIH2 is an interventional target of secondary damage following ICH." (PMID 35732617, 2022).
Parkinson disease (1 paper, 2012). A progressive degenerative disorder of the central nervous system characterized by loss of dopamine producing neurons in the substantia nigra and the presence of Lewy bodies in the substantia nigra and locus coeruleus. "The RBR family of E3 ligases include human E3 ligases such as the human homolog of DrosophilaAriadne (HHARI; also known as ARIH1) that shares homology with Hel1, as well as TRIAD1 (or ARIH2) and Parkin (or PARK2), the latter of which has been implicated in a subset of Parkinson's disease." (PMID 22570702, 2012).
spinobulbar muscular atrophy (1 paper, 2025). "Illustrative examples include mutations in ARIH2 associated with neurodevelopmental disorders such as autism and intellectual disability, and the role of HOIP in accelerating neurodegeneration in spinobulbar muscular atrophy (SBMA)." (PMID 40243483, 2025).
stomach carcinoma (1 paper, 2022). "Further bioinformatics analysis of the ASCL2 in STAD patients using the cBioPortal and GEPIA system shows that the ASCL2 may be related to CNTNAP3, CLIP1, C9orf84, ARIH2, and IL1R2 mutations and involved in stomach carcinoma prognosis, which requires further verification in future studies." (PMID 36008864, 2022).
tumor (9 papers, 2015 to 2026). "Additionally, residual tumor (R0, HR=1.46, P=0.049) was also associated with a higher ARIH2 expression level." (PMID 40260250, 2025). "Loss of ARIH2 alone had little effect on tumor growth in the vehicle treatment group." (PMID 31741433, 2019). "Through these two genome-wide screens and integration with CRISPR knockout datasets from T cells, MED12, CCNC, and ARIH2 were identified as candidate genes whose knockout enhances the anti-tumor response of NK cells." (PMID 41139700, 2026). "We also inspected the expression of ARIH2 in human tumor tissues and Paracancerous tissues by means of the TCGA dataset." (PMID 40260250, 2025). "In this study, we investigated the mRNA expression levels of ARIH2 across various tumor types and their corresponding adjacent normal tissues using the TCGA and GTEx databases." (PMID 40260250, 2025). "Our study discovered that ARIH2 was up-regulated in HCC tumor tissues compared with the control group." (PMID 40260250, 2025). "Immunohistochemical staining was also performed and showed that the rate of Ki67-positive cells was significantly inhibited in the GC tumor formed by ARIH2-knockdown GC cells treated by 5-fluorouracil." (PMID 35732617, 2022). "We further detected the expression of ARIH2 in tumor tissues and peritumoral tissues, and found that expression of ARIH2 was significantly upregulated in the tumor tissues." (PMID 35732617, 2022). "The results showed that the expression of ARIH2 in the tumor tissue of GC patients was higher than that in normal tissues." (PMID 35732617, 2022). "To verify the relationship between the prognosis of GC patients and the expression of ARIH2, we performed immunohistochemical staining to detect the expression of ARIH2 in normal tissues and tumor tissue of GC patients." (PMID 35732617, 2022). "ARIH2 is a RING-in-between-RING E3 ligase gene, its encoding protein has tumor suppressive function and also involves in the neuronal response to hypoxia." (PMID 35111198, 2021). "Collectively, these results imply that ARIH2 may play a crucial role in tumor immune evasion and antitumor immunity in HCC pathogenesis." (PMID 40260250, 2025). "Next, immunohistochemical staining was performed on tumor samples from mice with subcutaneous tumors and showed that the rate of Ki67-positive cells was significantly rescued after downregulation of p21 expression in the ARIH2-knockdown GC cells." (PMID 35732617, 2022). "ARIH2 expression could effectively distinguish tumor tissues from normal liver tissues." (PMID 40260250, 2025). "To determine whether ARIH2 enhances the tumor progression by promoting the proliferation of GC cells, we performed immunohistochemical staining and the results showed that the expression of ARIH2 and Ki67 in the ARIH2-knockdown tumors was significantly decreased." (PMID 35732617, 2022). "Research has demonstrated that ARIH2 expression is elevated in HCC tissue samples, exhibiting significant correlations with the clinical stage, histopathological grade, and tumor characteristics of HCC." (PMID 40260250, 2025). "While HUWE1, UBR5, PRPF19, ARIH2 and OBI1 are mainly related to tumor suppression, DNA damage response and DNA replication, TRIM21 is involved in regulating host innate immunity and viral immune evasion." (PMID 38932241, 2024). "For measurement of the proliferation of the control and ARIH2-knockdown GC cells, Western blot, MTT, BrdU, plate cloning, soft agar and tumor xenograft analysis were successively performed." (PMID 35732617, 2022). "Firstly, while we have investigated the association between ARIH2 and immune infiltration as well as ferroptosis in HCC patients, functional experiments to confirm the role of ARIH2 in modulating the HCC tumor microenvironment are absent." (PMID 40260250, 2025). "However, in an orthotopic mouse model implanted with PATC148 tumors, only CCNC and ARIH2 double knockout CAR-NK cells—not MED12-knockout CAR-NK cells—were able to significantly reduce tumor burden." (PMID 41139700, 2026).
cancer (7 papers, 2010 to 2025). A tumor composed of atypical neoplastic, often pleomorphic cells that invade other tissues. "However, further studies are necessary to elucidate the underlying molecular mechanisms by which ARIH2 influences cancer progression." (PMID 40260250, 2025). "A significant association between ARIH2 expression and normal tissue was noted in 24 of 33 cancers." (PMID 40260250, 2025). "The findings indicate that ARIH2 is upregulated in a variety of human cancers, particularly in LIHC." (PMID 40260250, 2025). "The mRNA expression profile of ARIH2 in pan-cancer and normal tissues was retrieved from the TCGA and GTEx databases." (PMID 40260250, 2025). "We discerned that ARIH2 expression was significantly elevated in 9 of 23 cancers compared with Paracancerous tissue." (PMID 40260250, 2025). "The Wilcoxon rank sum test was utilized to appraise the differential expression of ARIH2 in pan-cancer." (PMID 40260250, 2025). "Studies have demonstrated that ARIH2 induces apoptosis and clonogenic inhibition in myeloid cells with RING-dependent E3 ligase activity and that ARIH2 inhibits cell and clone growth by inducing apoptosis in several cancer cell lines." (PMID 35732617, 2022). "Ariadne homolog 2 (ARIH2) has been demonstrated to be upregulated in various human cancer tissues." (PMID 40260250, 2025). "Recent studies have investigated the regulatory function of ARIH2 in multiple malignant cancers." (PMID 40260250, 2025). "In addition, it has been reported that ARIH2 can induce apoptosis in several cancer cell lines including MCF7, A549 and U2OS, via its RING ligase activity." (PMID 35732617, 2022). "Previous studies have reported that RNF14, RNF31, RNF144B, RNF216 and ARIH1 mainly play carcinogenic roles, while ARIH2 and PARK2 generally play anticancer roles in malignant tumors." (PMID 35732617, 2022). "For example, CD44, ARIH2, CSDE1 (also known as UNR), CYB5B, SF3B1, and RCN2, which have been reported to be overexpressed in cancer, showed an increased proportion of shorter 3′-UTRs, primarily as a result of alternative cleavage and polyadenylation (APA)." (PMID 40702779, 2025). "Whereas, cancer cells lacking the ARIH2 protein were able to produce more proteins that are needed for cancer cell growth, which resulted in them having increased resistance to EGFR inhibitors." (PMID 31741433, 2019). "DEF8, NDUFC2, GUSBP1, ARIH2, STX12 and HIST1H2BN were highly re-expressed (more than 100 folds) in either treatment of MV4-11, have not been previously discussed on their role in cancer except for HIST1H2BN." (PMID 32337016, 2020).
infection (2 papers, 2025). The state of being infected such as from the introduction of a foreign agent such as serum, vaccine, antigenic substance or organism. "As a key regulator of inflammatory response, ARIH2 is important in defense against infection and had been demonstrated to regulate NLRP3 activity in microphages by ubiquitination." (PMID 40953119, 2025). "Co-transfection and co-infection experiments showed that both YTHDC1 and its W378A mutant, but not the YTHDC1 ∆IDR variant, were able to prevent ARIH2-induced degradation of PPARγ in HEK293T cells, primary brown adipocytes, and primary white adipocytes." (PMID 40355558, 2025).
neurodegenerative disease (1 paper, 2024). A disorder of the central nervous system characterized by gradual and progressive loss of neural tissue and neurologic function. "Of the 619 detected genes, 227 have previously been implicated in cognitive function, education, neuroticism, neuropsychiatric disorders, neurodegenerative diseases, and reaction time, such as ARIH2 and PTCH1." (PMID 38190638, 2024).
ARIH2 also shares sentences with these, for which no sentence is quoted: Bladder Cancer (1 paper); brain inflammation (1); brain injury (1); depression (1); diabetes (1); Glioblastoma multiforme (1); HIV-1 infection (1); injury (1); lung carcinoma (1); lymph node metastasis (1); mesothelioma (1); non-small cell lung carcinoma (1); prostate carcinoma (1); rectum adenocarcinoma (1); sarcopenia (1).